CYP11A1 (cytochrome P450 family 11 subfamily A member 1)
Diseases named in the same sentence as CYP11A1 in open-access papers (continued):
Sharing a sentence is not in itself a finding about the gene and the disease.
depression (1 paper, 2026). "Behavioral and reproductive assessments included depression-like behavior tests, sexual behavior, sperm quality, testicular histopathology, steroidogenesis proteins (AR, CYP11A1, StAR), and apoptosis markers (Hsp70, caspase-3, caspase-9)." (PMID 41598271, 2026).
embryonal carcinoma (1 paper, 2025). A non-seminomatous malignant germ cell tumor characterized by the presence of large germ cells with abundant cytoplasm resembling epithelial cells, geographic necrosis, high mitotic activity, and pseudoglandular and pseudopapillary structures formation. "Expression of genes involved in general steroid biosynthesis (STAR, POMC, CYP11A1, FDX1) and the aromatase-coding gene CYP19A1 was the highest in embryonal carcinomas." (PMID 40011822, 2025).
endometrial cancer (1 paper, 2022). Primary or metastatic malignant neoplasm involving the endometrium (mucous membrane that lines the endometrial cavity). "Regarding CYP11A1, the presence of specific single nucleotide polymorphisms in its gene has been associated with a higher risk of endometrial cancer." (PMID 36614002, 2022). "The expression of StAR, CYP11A1 and 3βHSD has also been reported in human endometrial cancer cell lines HHUA (estrogen (ER) and intracellular progesterone receptors (PR) positive; differentiated phenotype) and HOUA-1 (ER and PR negative, undifferentiated phenotype)." (PMID 36614002, 2022).
gonadotroph adenomas (1 paper, 2013). "Two such genes, CYP11A1 and NUSAP1, were analyzed in 39 human gonadotroph adenomas by qRT-PCR and found to be up-regulated in 77 and 95 % of cases, respectively." (PMID 23756599, 2013).
granulosa cell tumor (1 paper, 2023). A slow-growing, malignant tumor, characterize by the presence of granulosa-like cells and Call-Exner bodies, that is almost always found in the ovary. "Cyp11a1 acts upstream of the hormone biosynthetic process, and Greb1 has been reported to be induced by E2 in granulosa cell tumors through an ERα-dependent mechanism." (PMID 38031019, 2023).
hyperuricemia (1 paper, 2023). An abnormally high level of uric acid. "Compared with the control mice, the mRNA levels of enzymes such as cytochrome P450 family 11 Subfamily a member 1 (CYP11A1), 11β-hydroxylase (CYP11B1), aldosterone synthase (CYP11B2) and 3β-hydroxysteroid dehydrogenase 1 (HSD3B1) were significantly lower in the adrenal of hyperuricemia mice." (PMID 38034015, 2023).
hypogonadotropic hypogonadism (1 paper, 2021). Abnormal ovarian or testicular function due to insufficient hormonal stimulation from the hypothalamic-pituitary axis. "For example, boys with X-linked adrenal hypoplasia (NR0B1/DAX-1) are at risk of developing hypogonadotropic hypogonadism in adolescence, whereas there is a potential risk of long-term sex steroid insufficiency or hypofertility with partial defects in STAR or CYP11A1/P450scc." (PMID 34258490, 2021).
ischemic stroke (1 paper, 2020). A stroke disorder caused by obstruction of blood flow to the brain, due to thrombotic (local blood clot formation) or embolic (due to a blood clot or other material traveling from another site) event. "This study aimed to investigate the roles of CYP3A4 and CYP11A1 variants in ischemic stroke (IS) susceptibility among the Han Chinese population." (PMID 32126981, 2020).
male infertility (1 paper, 2023). The inability of the male to effect fertilization of an ovum after a specified period of unprotected intercourse. "Intersection of genes from transcriptomic studies with genes with identified rare variants revealed a total of 7 genes linked with male infertility phenotype (CYP11A1, CYP17A1, RSPH3, TSGA10, AKAP4, CCIN, NDNF)." (PMID 37670815, 2023).
myopia (1 paper, 2019). "The major product of novel cytochrome P450scc (CYP11A1)-initiated pathway of vitamin D3 metabolism, 20-hydroxyvitamin D3 (20(OH)D3), and its metabolites may have anti-proliferative, pro-differentiation, and anti-inflammatory effects, which could prevent myopia." (PMID 30677087, 2019).
non-small cell lung carcinoma (1 paper, 2024). A group of at least three distinct histological types of lung cancer, including non-small cell squamous cell carcinoma, adenocarcinoma, and large cell carcinoma. "Referring to a prior study on non-small cell lung cancer regarding in situ production of progesterone, we further observed whether the steroidogenic enzymes (StAR, CYP11A1, HSD3B2) are present and functional in PDAC cells." (PMID 38424455, 2024).
osteosarcoma (1 paper, 2024). A usually aggressive malignant bone-forming mesenchymal neoplasm, predominantly affecting adolescents and young adults. "We also revealed that loss of USP7 inhibited the E2 content and enzymes Cyp19a1 and Cyp11a1, which suggested that mTORC1 stabilized USP7 may positive regulate E2 synthesis in osteosarcoma." (PMID 38467635, 2024).
Ovarian Hyperandrogenism (1 paper, 2021). Increased production of androgens by the ovaries. "PAE could reduce the excessive testosterone in theca cells through downregulation of CYP17A1 and CYP11A1, which provided scientific evidence for the treatment of ovarian hyperandrogenism with PAE." (PMID 33638949, 2021).
pituitary adenomas (1 paper, 2013). "In vitro studies demonstrated for the first time that Cyp11a1 is a target of SF-1 in gonadotroph cells and promotes proliferation/survival of rat pituitary adenoma primary cells and cell lines." (PMID 23756599, 2013).
pituitary tumor (1 paper, 2013). A benign or malignant neoplasm affecting the pituitary gland. "We used somatotroph adenoma-derived GH3 cells, which express relatively high levels of Cyp11a1, to evaluate the effect of modulating gene expression on pituitary tumor cell proliferation." (PMID 23756599, 2013).
prostate adenocarcinoma (1 paper, 2023). "SEMA3C expression is correlated with expression of steroidogenic enzymes CYP11A1 and SRD5A2 as well as the AR target gene, FKBP5, in prostate adenocarcinoma patients according to TCGA PanCancer dataset available on cBioPortal." (PMID 37800655, 2023).
pulmonary fibrosis (1 paper, 2024). Chronic progressive interstitial lung disorder characterized by the replacement of the lung tissue by connective tissue, leading to progressive dyspnea, respiratory failure, or right heart failure. "At the same time, it is worth noting that there is practically no data on CYP11A1-mediated vitamin D derivatives in relation to pulmonary fibrosis." (PMID 39201632, 2024).
skin aging (1 paper, 2024). The gradual irreversible changes in structure of skin that occur as a result of the passage of time.. "Therefore, the treatment of skin aging and damage caused by photoaging can be considered to improve the activity of CYP11A1 as a target." (PMID 38621674, 2024).
vitamin D deficiency (1 paper, 2024). A nutritional condition produced by a deficiency of VITAMIN D in the diet, insufficient production of vitamin D in the skin, inadequate absorption of vitamin D from the diet, or abnormal conversion of vitamin D to its bioactive metabolites. "Enzymes like StAR, 17β-HSD, 3β-HSD, CYP11A1, and CYP17A1 are crucial for androgen synthesis in Leydig cells, with calcitriol shown to up-regulate CYP11A1 and CYP17A1 and increase 3β-HSD levels; conversely, vitamin D deficiency can decrease StAR, 3β-HSD, CYP11A1, and CYP17A1 expression in the testes." (PMID 38698459, 2024).
tumor (29 papers, 2013 to 2026). "This association between the CYP11A1-RORα/γ pathway and tumor progression suggests that activation of the alternative vitamin D metabolism pathway could be a novel preventive, as well as therapeutic, strategy for cancer." (PMID 29657326, 2018). "To investigate if HOXB9 can promote tumour formation we bred Sf-1:Hoxb9 mice with mice containing the activating conditional Ctnnb1 deletion allele and a construct with Cre recombinase driven by Cyp11a1-regulatory sequences (Ctnnb1 mutant mice, referred to as ABC)." (PMID 33214683, 2021). "Cyp11a1 activity, therefore, can mediate bidirectional communication between local autonomic and sensory nerves, and the tumour, with putative effects on the brain, is also envisioned." (PMID 40287432, 2025). "The marked decline in tumour growth in the Cyp11a1cKO mice underscored CYP11A1’s significance and promises for its use as a drug target." (PMID 40287432, 2025). "Previously, it has been shown that genetic deletion or pharmacologic inhibition of Cyp11a1 improves anti-tumor immunity and restricts experimental tumor growth." (PMID 40454094, 2025). "Modern advances in single-cell technologies offer in-depth characterisations of tumour-infiltrating immune cells, and our use of single-cell transcriptomics approach revealed the profound influence of CYP11A1 on immune cell infiltration." (PMID 40287432, 2025). "Genetic and pharmacological studies targeting CYP11A1, a key enzyme in steroidogenesis, have suggested the potential of modulating this pathway to reinvigorate anti-tumor immunity." (PMID 40454094, 2025). "All in all, our findings show that the genetic targeting of Cyp11a1 in immune cells curtails the growth of TNBC tumours and impinges upon the infiltration of immunosuppressive cells within the TME." (PMID 40287432, 2025). "As expected, FceR1+cKit+SiglecF− mast cells in tumours from the Cyp11a1-mCherry reporter mice distinctly displayed mCherry signals." (PMID 40287432, 2025). "Tumour restriction because of Cyp11a1 deletion underscore the therapeutic potential of targeting steroidogenesis, by stimulating immune responses against TNBC." (PMID 40287432, 2025). "To verify the colocalization between CagA and CYP11A1, we performed immunofluorescence staining in GC cells and mice subcutaneous tumour tissue." (PMID 39113698, 2024). "Nonetheless, our own data demonstrate that high CYP11A1 expression results in increased tumour growth and reduced patient survival." (PMID 36861295, 2023). "The tumor-promoting effect of CYP11A1 in macrophages and tumor-suppressing effect of intratumor metyrapone administration were proposed to be due to their respective actions in driving and inhibiting glucocorticoid synthesis." (PMID 37471141, 2023). "The steroidogenic enzyme CYP11A1 exhibited remarkably intense staining in all tumours, including in low grade tumours, suggesting the steroidogenic phenotype is present early during tumour initiation." (PMID 37564373, 2023). "E0771/Bone and B16F10 tumor cells that expressed Cyp11a1 were capable of forming bone metastases in mice." (PMID 38139309, 2023). "This highlights a role for Cyp11a1 in the anti-tumor immunity response and shows the direct involvement of steroidogenesis in promoting immunosuppressive activity of tumor-infiltrating Th2 cells." (PMID 35945203, 2022). "We confirmed changes in macrophage characteristics at the protein level, showing a significant decrease in Arg1+ macrophages (M2) with coincident increase in tumor-infiltrating iNOS+ macrophages (M1) upon T cell-specific Cyp11a1 deletion." (PMID 32680985, 2020). "Having identified presence of Cyp11a1-expressing T cells in established tumors, we next examined expression dynamics during tumor progression." (PMID 32680985, 2020).
tumor (continued). "The steroidogenesis-inducing type-2 cytokines such as IL4 are also often present in the TME31,32, thus we next sought to examine the steroidogenic capacity (i.e. Cyp11a1 induction) of T cells infiltrating tumors, and their impact on tumor development." (PMID 32680985, 2020). "Together, these data demonstrate the potential to stimulate anti-tumor immunity through pharmacological suppression of Cyp11a1-dependent steroidogenesis pathways." (PMID 32680985, 2020). "Altogether these data suggest that inhibition of T cell steroidogenesis by genetic deletion of Cyp11a1 changes immune cell composition in the tumor microenvironment in favor of anti-tumor immunity." (PMID 32680985, 2020). "This Cyp11a1 expression has pro-tumour functions as T cells’ specific deletion of Cyp11a1 leads to reduced tumour growth, using mouse tumour models." (PMID 32998240, 2020). "Genetic deletion of Cyp11a1 in T cells significantly restricted primary tumor growth rates and final volumes." (PMID 32680985, 2020). "Cyp11a1-mCherry− cells representing the cells that are most frequently available cells within B16-F10 tumor, namely B16-F10 cells and macrophages." (PMID 32680985, 2020). "The dominant Cyp11a1+ tumor-infiltrating immune cells were identified as T cells, predominantly CD4+ (helper T cells)." (PMID 32680985, 2020). "Genetic ablation of Cyp11a1 in T cells restricts experimental primary tumor growth and lung metastasis." (PMID 32680985, 2020). "The dominating CYP11A1 transcript was shared between all tumours and corresponded to the APPRIS P1 transcript." (PMID 31000732, 2019). "qRT-PCR showed that rat primary PA cells maintain the high Cyp11a1 expression level observed in the tumor tissues from which they derive, and thus represent a suitable model for analyzing the effect of gene knock-down." (PMID 23756599, 2013). "Therefore, in this study, we aimed to identify a new inhibitor of CYP11A1 and test its anti-tumor efficacy." (PMID 40454094, 2025). "Based on mice model-based experimental evidence, it has been proposed that targeting CYP11A1 may reinstate anti-tumor immunity." (PMID 40454094, 2025). "Recent studies have shown that CYP11A1, which converts cholesterol into the steroid pregnenolone, is expressed by T cells and macrophages and its expression in each of these cells functions to promote tumor growth." (PMID 37471141, 2023). "The silencing of Cyp11a1 in such cells was correlated with significant tumor growth inhibition." (PMID 36614002, 2022). "Moreover, the molecular mechanism of CYP11A1 should be further explored in 3D in vitro tumor models." (PMID 36182900, 2022). "Importantly, in both tumor models, pharmacological inhibition of Cyp11a1 by aminoglutethimide (AG) was sufficient to recapitulate the tumor restriction phenotype resulting from Cyp11a1 genetic ablation." (PMID 32680985, 2020). "Hence deletion of Cyp11a1 in T cells was sufficient to remodel the TME for more effective anti-tumor immune responses." (PMID 32680985, 2020). "Similar to the genetic deletion of Cyp11a1, application of the Cyp11a1 inhibitor aminoglutethimide significantly increased frequencies of M1 macrophages and degranulating T and NK cells, recapitulating anti-tumor phenotypes." (PMID 32680985, 2020). "Cyp11a1 inhibition also decreased the number of M2 macrophages in the tumor." (PMID 32680985, 2020). "To determine whether Cyp11a1 induction in T cells is conserved in other tumor types we analyzed an EO771 orthotopic model of breast cancer." (PMID 32680985, 2020). "The median CYP11A1 mRNA level in the CRPC metastases was 0.41 times compared to the level in the primary tumor tissue (P = 0.011), while the CYP17A1 and HSD3B2 mRNA levels in CRPC bone metastases were not significantly different from levels in the primary tumor tissue." (PMID 24244276, 2013). "In the future, CYP11A1 IHC may help diagnose the steroidogenic tumours to stratify patients." (PMID 40287432, 2025).
tumor (continued). "However, even if the level expression of CYP11A1 is low, pregnenolone synthesis could also occur in tumor cells independently of the CYP11A1." (PMID 36614002, 2022). "All these findings suggest that CYP11A1 might exert anti-tumor effects on RCC." (PMID 36182900, 2022). "However, there is evidence that Cyp11a1 is expressed in tumour-infiltrating T cells." (PMID 32998240, 2020). "Importantly, steroidogenesis inhibition by deleting Cyp11a1 (Cyp11a1cKO mice) effectively countered these GC-induced alterations, as revealed by up-regulated genes from RNA-seq data, in tumour infiltrating DCs of Cyp11a1cKO tumour-bearing mice compared to control tumour bearing mice." (PMID 40287432, 2025). "By eliminating CYP11A1-mediated steroidogenesis in immune cells, we ventured to understand its influence on TNBC tumour progression." (PMID 40287432, 2025). "Intratumoral administration of aminoglutethimide, which inhibits synthesis of pregnenolone and estrogens, or metyrapone, which inhibits CYP11A1 and 11β-HSD1 production of corticosterone, has been used to reduce tumor growth in vivo." (PMID 37471141, 2023). "Consistent with enhanced tumor immunity, we found significantly higher levels of the inflammatory cytokines Ifnγ and Tnfα expression in CD8+ T cells following Cyp11a1 ablation." (PMID 32680985, 2020). "Following the implantation of the E0771.LMB cells into Cyp11a1-mCherry reporter mice, we profiled the steroid hormones by LC-MS/MS, and isolated CD45+mCherry+ and CD45−mCherry− tumour-residing immune cells for in-depth scRNA-seq and flow cytometric assessments." (PMID 40287432, 2025). "The genetic deletion of Cyp11a1 by CRISPR/Cas9 mutagenesis in tumor cells or pharmacological inhibition of Cyp11a1 using aminoglutethimide protected animals from skeletal lesion formation and tumor-induced osteolysis in vivo." (PMID 38139309, 2023). "Again, we found that Cyp11a1 was upregulated in tumor-infiltrating T cells, but not in tumor-draining lymph node or spleen." (PMID 32680985, 2020). "Cyp11a1 expression was detected in immune cells of established primary tumors, but not in tumor-draining brachial lymph nodes (LN) or blood, indicating that stimulation occurs in situ." (PMID 32680985, 2020). "Moreover, analysis of human tumor-infiltrating CD4+ T cell transcriptomes, confirmed CYP11A1 expression implying that CD4+ T cells are a source of steroids in tumors, mirroring the murine setting." (PMID 32680985, 2020). "Of interest, while we have seen significant differences in overall patient survival between tumours with high versus low CYP11A1 expression, we have not been able to conduct the same analysis for CYP11B1, as expression was not reported for all tumour tissues summarized in the TCGA database." (PMID 36861295, 2023). "Reinterpretation of these data might instead suggest that myeloid CYP11A1–derived pregnenolone or vitamin D derivatives, rather than glucocorticoids, promoted tumor growth." (PMID 37471141, 2023). "Interestingly, while high CYP11A1 and HSD11B1 expression resulted in poor survival, suggesting that tumours efficiently suppressing the immune system via glucocorticoids have a growth advantage, high NR0B2 was beneficial for survival, likely due to increased suppression of LRH‐1." (PMID 36861295, 2023). "On a genetic level, a comparable study in a set of 20 paired samples of tumour and adjacent normal breast tissues from patients with infiltrating ductal carcinoma identified the expression of CYP1B1, CYP2B6, CYP2C, CYP2D6, CYP2E1, CYP4B1 and CYP11A1 in both tumour and control tissues." (PMID 33809117, 2021). "The presence of tumor cells did not induce or augment the Cyp11a1 expression in T cells in vitro." (PMID 32680985, 2020). "The presence of Cyp11a1+ non-T cells indicates that in a different context, such as in different tumor types, the steroidogenic population may vary and other hematopoietic cells may also produce steroids." (PMID 32680985, 2020).
tumor (continued). "We observed that SF-1 and P450scc are co-expressed in PA cells of MENX-affected animals, and both siRNA-mediated silencing of the Nr5a1 gene and treatment with the SF-1 inhibitor IsoQ resulted in the down-regulation of Cyp11a1 in rat primary tumor cells and in LβT2 gonadotroph cells." (PMID 23756599, 2013). "We generated STAR knockout (KO) MA-10 mouse tumor Leydig cells and showed that STAR KO cells failed to form progesterone in response to dibutyryl-cAMP and to TSPO drug ligands, but not to 22(R)-hydroxycholesterol, which is a membrane-permeable intermediate of the CYP11A1 reaction." (PMID 33670702, 2021).